IL10 (interleukin 10)
Diseases named in the same sentence as IL10 in open-access papers (continued):
Sharing a sentence is not in itself a finding about the gene and the disease.
Sepsis (continued). "Interestingly, IL-10, an anti-inflammatory cytokine, has a negative impact on the production of proinflammation cytokines, whereas the elevation of serum IL-10 levels is also correlated with the development of sepsis and even the risk of mortality in burn patients." (PMID 33654698, 2021). "Additionally, TNFA and IL10 variations have been associated with sepsis development." (PMID 30862128, 2019). "Thus, whilst haemolysis (as measured by low HPX, reflecting cumulative exposure to haem) and IL-10 are both associated with markers of inflammation (IL-6, TNFα, and G-CSF), IL-10 is most closely associated with raised HO-1 in sepsis patients at the time of admission." (PMID 30046137, 2018). "Finally, genetic variations could also contribute to the IL-10 dual role since IL-10 promoter polymorphisms were associated with lower LPS-dependent IL-10 production and with the development of sepsis in patients with major trauma." (PMID 29974037, 2018). "Additionally, HO-1 deficiency blocks the anti-inflammatory action of IL-10 in a sepsis model." (PMID 28698513, 2017). "Therefore, injection of recombinant adenovirus expressing IL-10, which limits DC maturation and associated T cell activation, could attenuate acute sepsis." (PMID 25821827, 2015). "The gene encoding IL-10 cytokine involved in the modulation of inflammatory responses as a main anti-inflammatory agent is therefore a candidate gene for determination of the human genetic background, which is responsible for inter individual differences in susceptibility to sepsis development." (PMID 26561011, 2015). "However, recent research on the pathophysiologic mechanisms underlying sepsis indicates that the profound proinflammatory response is counteracted by certain anti-inflammatory cytokines, including IL-10, transforming growth factor (TGF-β), and IL-4, which attempt to restore immunological balance." (PMID 25614712, 2014). "Due to its anti-inflammatory and immunosuppressive activity, IL-10 may initially control the exaggerated pro-inflammatory wave of early mediators in sepsis; however persistent high levels of IL-10 can cause immunoparalysis and eventually lead to poor outcome in septic shock." (PMID 23561467, 2013). "This conundrum raises the possibility whether locally applied IL-10 strategy could possibly protect end organs by changing their inflammatory microenvironment without altering the systemic inflammatory response and the susceptibility to infection and sepsis." (PMID 22046081, 2012). "The main objective of this study was to determine whether early measurements of IL-6 (interleukin-6) and IL-10 plasma concentrations (as markers of initial severity) could improve, in association with mHLA-DR recovery, the prediction of sepsis occurrence in severe trauma patients." (PMID 22431998, 2012). "Persistently high plasma IL-10 level may cause sepsis-induced immunosuppression and death." (PMID 21939530, 2011). "The objectives of this prospective study were to investigate the distribution of IL-10 promoter polymorphisms in a cohort of 308 Chinese Han patients with major trauma, and to identify associations of IL-10 promoter polymorphisms with IL-10 production and incidence of sepsis and MODS." (PMID 19939284, 2009). "Therefore, it is reasonable that lower IL-10-producing -1082 AA genotype might be used as a relevant risk estimate for organ dysfunction and sepsis in trauma patients." (PMID 19939284, 2009). "Further studies are needed to confirm the clinical relevance of the IL-10 promoter polymorphisms in a larger cohort of trauma patients and to investigate the relation of these SNPs with other genetic polymorphisms in prediction of sepsis and outcome in trauma patients." (PMID 19939284, 2009).
Sepsis (continued). "In this study we investigated whether the genetic variations at positions -1082, -819 and -592 in the IL-10 promoter affect IL-10 production after trauma, and whether there is an association of these polymorphisms with the development of post-traumatic sepsis and MODS." (PMID 19939284, 2009). "In vivo, azaserine treatment in cecal ligation and puncture-induced sepsis reduced IL-10, increased TNF-α, and elevated bacterial burden." (PMID 41756441, 2026). "Sleep interruption also increased the levels of serum cytokines (including IL-23 before sepsis was induced, and IL-6, TNF-α, MCP-1, and IL-10 after sepsis), and amplified macrophage cytokine production ex vivo." (PMID 42257268, 2026). "Serum levels of TLR2, TLR4, TLR9, IL-1β, IL-6, IL-8, IL-10, TNF-α and IFN-γ were quantified by enzyme-linked immunosorbent assay at the time of sepsis diagnosis." (PMID 41846925, 2026). "Conversely, excess IL10 induces immunosuppression in sepsis and increases mortality by impairing bacterial clearance in pneumococcal pneumonia." (PMID 41598258, 2026). "In the meantime, IL10 is related to down regulation of the inflammatory mediator production in sepsis." (PMID 41598258, 2026). "Pro‐inflammatory IL‐1β, IL‐6, IL‐8, IL‐12/23p40, TNF‐α, and IFN‐γ, and anti‐inflammatory (regulatory) cytokine IL‐10 play key roles in the acute phase of sepsis." (PMID 41474380, 2026). "IL‐10 is generally regarded as an anti‐inflammatory cytokine that suppresses excessive immune activation and tissue injury during sepsis." (PMID 41551210, 2026). "Pharmacokinetic variability, heterogeneous sepsis etiologies, and unmeasured key biomarkers like interleukin-10 further limit mechanistic insight." (PMID 41563955, 2026). "In sepsis patients, for example, hydrocortisone (cortisol) effectively reduces pro-inflammatory cytokines while boosting the anti-inflammatory cytokine IL-10." (PMID 41226310, 2025). "Some immunosuppressive factors, such as IL-10, have been reported to be involved in the immunosuppression of sepsis." (PMID 40185975, 2025). "Nominally pro- (IL-6, MIP-2, TNFα) and anti-inflammatory cytokines (IL-10) form a double-edged sword in sepsis and septic shock and are required to respond to, and eliminate infection, while excessive production causes organ damage." (PMID 41155249, 2025). "Enhance monocyte function in sepsis and counter immunosuppression by reducing IL-10, with a potential trade-off of increased PD-L1 impairing immunity." (PMID 40153575, 2025). "Next, wedetermined IL-10 and TGF-β production by MDSCs isolated from theS100A9-deficient mice during the late sepsis phase." (PMID 40458301, 2025). "MDSCs from wild-type mice and patients with late sepsis produced highamounts of IL-10 and TGF-β upon ex vivo stimulation withbacterial LPS." (PMID 40458301, 2025). "Wealso reported that the adaptive transfer of MDSCs from late septic mice into naivemice immediately after sepsis induction significantly increases circulating levelsof IL-10 and TGF-β." (PMID 40458301, 2025). "During the immunosuppressive phase of pediatric sepsis, anti-inflammatory cytokines, particularly IL-10, IL-4, and IL-13, play a central role in counterbalancing the initial hyperinflammatory response." (PMID 41300951, 2025). "Compared with the SIRS cohort, Sepsis_D patients exhibited higher levels of Calprotectin (p = 0.0072), Azurocidin (p < 0.0001), IL-4 (p = 0.0112), IL-8 (p = 0.0015), IL-10 (p = 0.0007), TNF-α (p = 0.0198), and IL-35 (p < 0.0001)." (PMID 41301767, 2025). "MCP-1, IL-6, and IL-10 levels are significantly elevated at d0 in both sepsis groups compared to healthy controls (p < 0.05)." (PMID 40510342, 2025). "Cytokines play a pivotal role in host defense during sepsis, with key mediators such as tumor necrosis factor-α (TNF-α), interleukin (IL)-1, IL-6, and IL-10 implicated in its pathophysiology." (PMID 40944015, 2025).
Sepsis (continued). "The consistent reduction in proinflammatory cytokines and upregulation of IL-10 across diseases like asthma, sepsis, and liver fibrosis highlight their immunomodulatory role." (PMID 41158310, 2025). "In sepsis, IL-10 reduces systemic inflammation and improves survival by suppressing pro-inflammatory cytokines like TNF-α and IL-6." (PMID 40076949, 2025). "To begin to understand how fluoxetine protects from sepsis-induced disease and mortality, we initiated lines of investigation to understand how fluoxetine regulation of IL-10 and triglycerides protect from organ dysfunction and damage." (PMID 39951524, 2025). "IL-10, an anti-inflammatory cytokine, can increase sepsis scores and mortality by diminishing inflammatory defenses and dampening immune responses." (PMID 40012626, 2025). "The release of IL-4 and IL-10 in sepsis suppress Th1 inflammatory response by reducing IFN-γ, TNF-α and IL-1β secretion by Th1 cells and inhibit Th1 cells polarization." (PMID 40364841, 2025). "Pro-inflammatory cytokines like IL-6, MCP-1, and IL-18 were elevated, as was the anti-inflammatory IL-10 in both sepsis cohorts compared to healthy controls." (PMID 40510342, 2025). "In sepsis, intracellular IL-10 production by monocytes and CD4+ T cells is significantly elevated, reflecting a state of systemic immunosuppression." (PMID 41300951, 2025). "As an anti-inflammatory cytokine, IL-10 modulates inflammation but, during sepsis, this effect can be detrimental since a dampened immune response can exacerbate disease progression." (PMID 40534875, 2025). "We show that these cells are induced in a relevant murine model of sepsis and in clinical samples from patients, where they exert suppressive effects on T cells through IL-10 production and elevated PD-L1 expression." (PMID 40155394, 2025). "IL-10+ regulatory T cells were present in lower proportions in sepsis patients compared to the proportion present in the healthy cohort (p=0.04)." (PMID 39935482, 2025). "Severe leptospirosis develops a cytokine storm characterized by high levels of IL-6, TNF-α, and IL-10, resembling sepsis-like phenotypes." (PMID 41445751, 2025). "Collectively, these findings suggest that both M2 macrophage proportions and IL-10 expression are diminished in sepsis, underscoring their critical roles in mitigating the progression of the condition." (PMID 41143725, 2025). "MDSCs primarily regulate T cells via IL-10 or PD-L1, but their effect on B cells in sepsis was unclear." (PMID 40185975, 2025). "Literature validation yielded 30 ultra-high confidence therapeutic candidates, including both established sepsis genes (IL10, TREM1, S100A9, NLRP3) and novel targets warranting investigation." (PMID 41071041, 2025). "Il-10 has a more protective effect during polymicrobial sepsis and has been shown to improve the survival of CLP-mice." (PMID 40253667, 2025). "Among inhibitory cytokines, IL-10 was evaluated in our study, and the most relevant finding was the significantly higher levels observed in Sepsis_D patients compared with Sepsis_A." (PMID 41301767, 2025). "Previous studies have shown that peritoneal acidosis suppressed the immune system by increasing serum IL10 and decreasing serum TNFα levels in rats with lipopolysaccharide (LPS)-induced sepsis." (PMID 40102905, 2025). "As sepsis progresses, an increasing number of Siglec-F+ neutrophils, which produce IL-10 and contribute to a suppressed immune response in the spleen, are observed in the spleens of mice." (PMID 40153575, 2025). "This differential response suggests the sepsis patients had already mounted a full response and had reduced their IL-10 production, so therefore were unable mount a full response on subsequent ex vivo stimulation." (PMID 39935482, 2025). "After ex vivo stimulation, sepsis samples had less of a reduction in CD4+ T cells producing IL-10 than healthy controls." (PMID 39935482, 2025).
Sepsis (continued). "Interleukin-10 (IL-10) is a key anti-inflammatory cytokine that plays a regulatory role in sepsis by limiting the host immune response to infection." (PMID 41013722, 2025). "IL-10’s anti-inflammatory role is evident in conditions such as sepsis, inflammatory bowel disease (IBD), and chronic infections." (PMID 40076949, 2025). "IL-10 is necessary for protection from sepsis-induced hypertriglyceridemia, preventing cardiac effects including impairment of glucose oxidation, ectopic lipid accumulation, ventricular stretch and possibly cardiac failure." (PMID 39951524, 2025). "Our description of IL-10-producing PCs with a regulatory function is also coherent with the fact that IL-10 has been repeatedly described as a major mediator of sepsis-induced immunosuppression." (PMID 40155394, 2025). "Our goal for the current study was to understand how prophylactic use of fluoxetine can protect from sepsis and determine the relationship between fluoxetine’s effects on IL-10 and triglycerides." (PMID 39951524, 2025). "Material and Methods: We analyzed recent clinical and experimental studies focusing on the most studied ILs—including IL-1, IL-6, IL-10, IL-8, IL-12, IL-18, and IL-17—in the pathophysiology of sepsis." (PMID 41300951, 2025). "IL-10 level was higher in sepsis (p<0.0001) and AOD (p=0.02) compared to the healthy control cohort." (PMID 39935482, 2025). "Second, as inflammation progresses to sepsis, compensatory anti-inflammatory mechanisms, including the release of IL-10, are activated to counterbalance excessive inflammation." (PMID 39926431, 2025). "Given the roles of IL-10 andTGF-β in enhancing sepsis-induced immunosuppression, these findings suggest that theS100A9 protein functions as a molecular immune repressor inlate sepsis via supporting MDSC suppressive functions." (PMID 40458301, 2025). "Interleukins are produced by many WBCs and are involved in the differentiation and activation of other immune cells, with IL-1β, IL-6, and IL-10 being the most studied in the context of sepsis." (PMID 39968295, 2025). "The anti-inflammatory cytokines interleukin-10 (IL-10) and lymphocyte depletion are two key features in the immunosuppressive mechanisms of sepsis." (PMID 41001389, 2025). "In the previously noted study regarding patients with ACLF and sepsis, the serum concentration of IL-10 was significantly increased compared to patients with ACLF or liver cirrhosis." (PMID 40429966, 2025). "Nevertheless, it is imperative to underscore the dualistic nature of the function of IL-10 in sepsis: it is both proinflammatory and anti-inflammatory." (PMID 40153575, 2025). "Future studies are needed to determine the mechanism by which fluoxetine regulates IL-10 and determine the contribution of each of these cell types in fluoxetine’s anti-inflammatory effects on regulating lipid homeostasis and sepsis disease progression." (PMID 39951524, 2025). "In the first hours after inducing sepsis conditions, there is an increase in pro-inflammatory response, and at 24 h, there is an increase in IL-10." (PMID 40429966, 2025). "Mechanistically, during the late immunosuppressive phase of sepsis, M2 macrophages are activated by Th2 cytokines (IL-4 and IL-13), LPS, glucocorticoids, IL-10, IL-6, or TGF-β." (PMID 40364841, 2025). "While enhancing early inflammatory responses, IL-27 paradoxically suppresses Th1/Th17 differentiation and potentiates IL-10 production from Tregs and type 1 regulatory T (Tr1) cells during late-phase sepsis." (PMID 40364841, 2025). "In more advanced stages, exosomes also carry anti-inflammatory cytokines (IL-4, IL-10), reflecting the biphasic nature of the immune response in sepsis." (PMID 41268545, 2025). "Fourth, the identification of the IL-10, Semaphorin 3e, and IL-17F as the top responders to the polymicrobial sepsis that are being suppressed by the NTCI." (PMID 41229427, 2025).
Sepsis (continued). "This in vivo targeting ofHotairm1 significantly reduced IL-10 and TGF-βproduction by MDSCs, further supporting that Hotairm1 couples withS100A9 to promote sepsis-induced immunosuppression byincreasing IL-10 and TGF-β levels during late sepsis." (PMID 40458301, 2025). "During sepsis, IL-10 is rapidly upregulated in response to pro-inflammatory cytokines such as TNF-α and IL-6." (PMID 41013722, 2025). "We have previously demonstrated that MDSCs from mice with late sepsis producehigh amounts of immunosuppressive cytokines such as IL-10 and TGF-β." (PMID 40458301, 2025). "One large-scale study found that patients with severe sepsis secondary to pneumonia had a significant increase in IL-6 and IL-10 levels one day after the onset of sepsis, with males showing higher levels compared to females." (PMID 40362448, 2025). "A recent clinical trial has shown that using the “our Methods”significantly restores levels of cTnI and pro-BNP in sepsis patients, reduce levels of inflammatory factors such as IL-6 and IL-10, and improve heart function." (PMID 40520010, 2025). "A novel finding of our study is the potential involvement of both calprotectin and IL-10 in this late immunosuppressive phase of sepsis." (PMID 41301767, 2025). "Together, these data demonstrate that IL-10 is necessary for the anti-inflammatory effects of fluoxetine and the protection from sepsis-induced disease and mortality mediated by fluoxetine pretreatment." (PMID 39951524, 2025). "The potent anti-inflammatory properties of IL-10 can be harnessed to treat acute inflammatory diseases related to sepsis." (PMID 40166075, 2025). "An outstanding question is: How does fluoxetine increase circulating levels of IL-10 during polymicrobial sepsis?" (PMID 39951524, 2025). "This study aimed to assess the performance of IL-10/lymphocyte ratio (ILR) and lactate (Lac) in the prognostic prediction and risk stratification of sepsis." (PMID 41001389, 2025). "For example, IL-10 proved valuable in distinguishing sepsis patients from healthy individuals, with an AUC of 0.8955, aligning with findings from other studies." (PMID 40264754, 2025). "To test the importance of IL-10 for fluoxetine mediated protection from sepsis, we subjected Il10−/− mice to our fluoxetine pretreatment paradigm and measured pro-inflammatory cytokine production." (PMID 39951524, 2025). "Luteolin protects lung tissue from SALI and reduces the excessive accumulation of IL-10 in the lungs during sepsis." (PMID 40012626, 2025). "Alterations to other immune cells can also induce a cytokine shift and monocytes, a major source of IL-10, can undergo leukocyte reprogramming or develop monocyte anergy during sepsis leading to elevated levels of this important cytokine." (PMID 40534875, 2025). "An animal study reported reduced serum interleukin-6 (IL-6), high mobility group protein B1 (HMGB)-1, and tumor necrosis factor-α(TNF-α) levels but increased interleukin-10 (IL-10) levels in the group given esmolol compared with the sepsis group." (PMID 40522976, 2025). "The most prominent cytokines in sepsis related immunosuppressive were IL-4, IL-10, IL-27, IL-37, IL-38 and TGF-β." (PMID 40364841, 2025). "Unsurprisingly, serum cytokines (TNF-α, IL-6, and IL-10) in probiotic-treated CLP sepsis mice were lower than in the untreated CLP group." (PMID 41444762, 2025). "Using whole-body Il10−/− mice, we found that the protective effects of fluoxetine pretreatment against sepsis were largely abolished." (PMID 39951524, 2025). "We also observed a more prominent inflammatory response in severe sepsis than in mild sepsis, with higher levels of IL-6 and IL-10 in 7 or 10-punctures CLP than in 4-punctures CLP." (PMID 39522078, 2024). "In murine sepsis and upon infection of immunocompromised mice with murine cytomegalovirus, NK cell-derived IL-10 was found to prevent an exacerbated immune response." (PMID 39355242, 2024).